IL4R (interleukin 4 receptor)
Diseases named in the same sentence as IL4R in open-access papers (continued):
Sharing a sentence is not in itself a finding about the gene and the disease.
pneumoconiosis (1 paper, 2011). An occupational lung disorder caused by inhalation of dust particles. "In the present study, we investigated the association between the potential functional polymorphisms in IL-4, IL-4R, and IL-13 and coal workers' pneumoconiosis (CWP) risk in a Chinese population." (PMID 21857939, 2011).
pneumonitis (1 paper, 2010). An inflammatory process affecting the lung parenchyma. "In combined analysis, the significant SNPs together with an additional borderline significant variant – IL4R: rs1801275 (P = 0.053) – showed an increase in pneumonitis risk as the number of unfavorable genotypes increased." (PMID 20811626, 2010).
pregnancy disorder (1 paper, 2021). A disorder that is related to pregnancy. "Moreover, the polymorphisms of IL4R gene are associated with the pregnancy disorders and various cancer types in humans." (PMID 33920608, 2021).
Pulmonary hemorrhage (1 paper, 2021). Pulmonary hemorrhage is a bleeding within the lungs. "In this model, induction of pulmonary hemorrhage and vasculitis was dependent on ILC2s and signaling through IL4Rα." (PMID 33974563, 2021).
retinal degeneration (1 paper, 2020). Degeneration of the retina. "The IL-4/IL-4Rα axis contributes to pathological angiogenesis through communications with bone marrow cells leading to retinal degeneration." (PMID 32366355, 2020).
RSV bronchiolitis (1 paper, 2014). "Each of the SNPs tested had previously been established to have a functional impact on immune responsiveness and two of the SNPs in the IL4 and IL4R genes had previously been associated with severe RSV bronchiolitis." (PMID 24949794, 2014). "The IL4 promoter and IL4R gene SNPs examined in this study have been reported to be associated with severe RSV bronchiolitis in children in Korea and the Netherlands, respectively." (PMID 24949794, 2014).
Salmonella Infections (1 paper, 2020). Infections with bacteria of the genus SALMONELLA. "With this gate, Salmonella infection caused ∼40% of infected cells to become IL-4Rα+ in DMSO-treated cells but only ∼10% of infected cells to become IL-4Rα+ in the CHIR99021-treated cells." (PMID 31862381, 2020). "Collectively, these data show that GSK3 kinase activity is required specifically for SteE- but not IL-10-mediated Y705-STAT3 phosphorylation and upregulation of the M2 marker IL-4Rα during Salmonella infection." (PMID 31862381, 2020).
steatosis (1 paper, 2021). Increased lipid within the cytoplasm of cells. "This suggests that IL-4Rα-deficient mice are not able to sufficiently metabolize fructose in their liver, which could contribute to decreased weight gain, improved steatosis and better glucose tolerance." (PMID 34302121, 2021).
tendinopathy (1 paper, 2010). "We found that primary human tenocytes derived from healthy tendon tissues and tendon segments involved in tendinopathy express the IL-13R and IL-4R chains except for γc." (PMID 20537133, 2010).
Thrombocytopenia (1 paper, 2019). A reduction in the number of circulating thrombocytes. "This reported protective effect could be a consequence of thrombocytopenia since mice with extracytoplasmic GPIbα domain genetic deletion (IL4R/GPIbα mice) develop milder thrombocytopenia and are not protected against atherosclerosis." (PMID 31572732, 2019).
thymoma (1 paper, 2018). A neoplasm arising from the epithelial cells of the thymus. "Whether IL-4Rα plays a role in the growth of thymoma and induces the T cells expressing specific TCRs to metastasize to periphery to participate in the production of AChR-Ab wait for further researches." (PMID 30042722, 2018). "We did not enroll thymoma patients without MG, therefore, the association between IL-4Rα gene polymorphism and thymoma should be further confirmed." (PMID 30042722, 2018). "The role of IL-4R on the pathogenesis in thymoma might resemble with those in other tumors." (PMID 30042722, 2018).
trypanosomiasis (1 paper, 2025). Infection with protozoa of the genus trypanosoma. "The current study used NLR to test if IL-4Rα inhibition adds further to the inflammatory burden in trypanosomiasis and it was seen that IL-4R inhibition promoted inflammation significantly." (PMID 40977748, 2025). "2.Enhancing IL-4Rα Signalling: Preservation or pharmacological enhancement of IL-4Rα activity could be a potential therapeutic strategy to boost anti-inflammatory responses, reduce neuroinflammation, and improve recovery in late-stage trypanosomiasis." (PMID 40977748, 2025).
type-2 diabetes (1 paper, 2023). "Despite the absence of monoclonal antibodies against known type-2 diabetes small molecule targets ABCC8, ABCC9, DPP4, and KCNJ11, these genes demonstrated AB tractability estimates greater than 60%, along with interleukin receptors IL4R and IL17RA." (PMID 37225853, 2023).
vasculitis (1 paper, 2021). "IL4Rα signaling was required for the development of vasculitis in hypereosinophilic mice." (PMID 33974563, 2021). "Because IL5Tg mice on ILC2del, STAT6–/– or IL4Rα–/– backgrounds had severe hypereosinophilia but few pulmonary intraparenchymal eosinophils and no vasculitis, we suspected that IL4Rα signaling might promote eosinophil migration into tissue." (PMID 33974563, 2021). "We surmise that some cases of EGPA may have been misdiagnosed as simple eosinophilic asthma in these trials rather than IL4Rα blockade leading to vasculitis per se." (PMID 33974563, 2021).
vitamin D deficiency (1 paper, 2025). A nutritional condition produced by a deficiency of VITAMIN D in the diet, insufficient production of vitamin D in the skin, inadequate absorption of vitamin D from the diet, or abnormal conversion of vitamin D to its bioactive metabolites. "Unlike the uniformly risk-amplifying effects of Th2-pathway variants (IL4R/IL-4/IL13) under vitamin D deficiency, MS4A2’s role is protective and vitamin D-dependent." (PMID 40927566, 2025).
tumor (173 papers, 1989 to 2026). "Whole-body fluorescence imaging revealed that DiD-labeled IL4R-Exo(si/mi) exosomes successfully reprogrammed tumor-associated macrophages (TAMs) into an M1 phenotype, thereby inhibiting tumor growth." (PMID 39865337, 2025). "Knockout of the IL-4 receptor (IL4rα) reduced physical interactions between tumor cells and IL4rα-deficient macrophages, correspondingly decreasing metastatic foci, indicating that IL-4 regulates macrophage-tumor cell interactions." (PMID 40995371, 2025). "Type II IL4R comprises the IL4Rα and IL13Rα subunits and is significantly upregulated in certain tumor types associated with poor prognosis." (PMID 40656893, 2025). "M1 macrophage-derived exosomes, engineered to promote M1 polarization and target IL4R, inhibit tumor growth by reprogramming tumor-associated macrophages (TAMs) into M1-like macrophages." (PMID 40034694, 2025). "One of the receptor chains of IL-4Rα was highly expressed in solid cancers and was closely associated with locally advanced tumor staging, promoting poor prognosis." (PMID 37117331, 2023). "While Il4r and Igf1 mRNA was expressed in Cd68/Aif1-positive tumour-associated microglia throughout drug-treated PDOX, Il4 expression co-localised with Gfap/S100b-expressing astrocytes exclusive to the interface region of drug-treated PDOX." (PMID 37127652, 2023). "The central role of IL4 signaling in MAMs was confirmed by high-resolution intravital imaging of the lung in mice at the time of metastatic seeding, which showed reduced physical interaction between tumor cells and IL4rα-deficient macrophages." (PMID 36077870, 2022). "High-resolution intravital imaging at the time of metastatic seeding showed reduced physical interaction between tumor cells and IL4rα-deficient macrophages, showing the dependence on IL4." (PMID 36077870, 2022). "Intravital imaging experiments showed that the physical interaction between tumor cells and metastasis-associated macrophages (MAMs) in the metastatic lung was reduced in IL4rα-deficient mice." (PMID 36077870, 2022). "Loss of IL-4Rα resulted in significantly higher tumor histological grades in Tslp-PyMttg Il4rKO mice associated with lung metastasis compared with Tslp-PyMttg mice (P = 0.001)." (PMID 35657353, 2022). "Tumor M-MDSCs expressed Arginase 1 (Arg1), consistent with a suppressive phenotype, and the genes encoding the IL-4Rα and IL-13Rα1 receptor subunits, suggesting their potential ability to respond to ILC2-derived cytokines IL-4 and IL-13." (PMID 35658010, 2022). "In this study, Nu-IL4Rα-positivity was significantly associated with higher tumor stage, presence of distant metastasis at diagnosis, and higher histologic grade." (PMID 35207737, 2022). "In the tumor microenvironment (TME), IL‐4 elicits an increased Th2 response and activates myeloid‐derived suppressor cells (MDSCs) and tumor‐associated macrophages (TAMs), both of which express the IL‐4R, to promote immunosuppression and angiogenesis." (PMID 33682324, 2021). "It has been shown that cancer initiating cells inhibited T cell proliferation in vitro via their membrane-associated IL-4 and IL-4R, while blocking IL-4-impaired tumor growth and stimulating antitumor T cell effectors." (PMID 33233582, 2020). "In vivo PDE5 inhibition reduced ARG1 and NOS2 and down-regulated IL-4Rα in tumour-associated MDSCs in BALB/c and C57BL/6 tumour-bearing mice." (PMID 29743944, 2018). "One of its receptor chains, IL-4Rα, was shown to be overexpressed in several solid human tumors and was associated with locally advanced tumor staging, increased propensity for metastases and poor overall survival." (PMID 28350325, 2017). "This possibility is supported by the additive inhibitory effects on tumor growth and macrophage accumulation observed both when apoptotic cells are removed from the graft and when IL-4Rα is deficient in the host." (PMID 25702581, 2015).
tumor (continued). "A study in mice showed that IL-4Rα competent murine tumors exhibited increased tumor growth when compared with tumors from IL-4Rα-deficient counterparts." (PMID 25208941, 2014). "IL‐4 plays a critical role in tumour development, being associated with aggressiveness and metastasis potential, and most recent studies indicate that endogenous IL‐4 can favour resistance to apoptosis via IL4‐R signalling." (PMID 38117000, 2023). "We used RT-qPCR to validate the differential expression of the five genes most strongly linked to inflammation and tumor immune responses: chemokine Ccl7, cytokine Csf2/GM-CSF, cytokine receptors Il4r and Il18r1, and inhibitor of antitumor immunity through antigen presentation Lilrb3." (PMID 36980301, 2023). "Additionally, the mRNA expression of Rab1A was closely associated with that of IL-4Rα in GC tumor tissues (P < 0.001)." (PMID 37117331, 2023). "One possible explanation might be that IL4Rα/IL13Rα1 are involved in tumorigenesis in association with nuclear proteins related to tumor biology." (PMID 33419470, 2021). "In addition, higher expression of IL4Rα and IL13Rα1 were associated with advanced clinicopathological factors of STSs such as higher tumor stage, cancer metastasis, higher histologic grade, increased mitosis, and tumor necrosis." (PMID 33419470, 2021). "Furthermore, several studies have reported that single nucleotide polymorphisms (SNPs) in the IL4R gene are closely associated with tumor progression." (PMID 31540495, 2019). "Consequently, it is only little surprising that the expression of IL-4 and IL-4Rα seems to be associated with malignant transformation in several tumor types." (PMID 28350325, 2017). "WNT/β-catenin pathway dysregulation is critical for tumour progression and growth suggesting that there may be a causal link between reduced tumour growth and β-catenin localization in IL-4Rα−/− tumours." (PMID 23784081, 2013). "However, recent reports have suggested that the high expression of IL4Rα and IL13Rα1 in tumor tissue might be associated with tumorigenesis in several kinds of tumor." (PMID 31540495, 2019). "Recent reports describing the association of circulating and tumour-infiltrating MDSCs with CRC progression in clinical studies highlight the potential relevance of these cells to the functional consequences of reduced IL-4R function during colorectal carcinogenesis." (PMID 23784081, 2013). "IL4, secreted by Th2 cells, binds to IL4R on tumor cells, leading to activation of signal transducer and activator of transcription 6 (STAT6) and the subsequent upregulation of GATA3 and IL4 expression." (PMID 39941924, 2025). "Cell surface receptors, especially IL-4Rα, are highly specific targets in PC therapy and can directly kill tumor cells overexpressing these receptors while reducing damage to normal tissues." (PMID 39958351, 2025). "We established autologous co-cultures of tumor and immune cells from primary human NSCLCs to study the functional impact of IL4Rα and/or PD-1 blockade using monoclonal antibodies." (PMID 40091029, 2025). "IL4R, a cell surface receptor that targets M2 macrophages in the tumor microenvironment, is classified into two types: Type I and Type II." (PMID 40656893, 2025). "Recent advances highlight the complex interplay between tumor-promoting and tumor-suppressing immune signals—such as IL-4Rα-driven progression and IL-24-mediated inhibition—as well as novel targets like ERBB2 and tumor-associated autoantigens." (PMID 40508013, 2025). "IL4 and IL4R can induce M2 macrophage polarization, thereby promoting tumor progression and metastasis." (PMID 40656893, 2025). "Reprograms IL4r-high and M2-polarized TAMs into an M1-like phenotype, thereby inhibiting tumor progression." (PMID 40496863, 2025). "NR1H4 and IL4R are promising immune-related diagnostic biomarkers for OCCC, with potential roles in neutrophil-mediated tumor microenvironment modulation." (PMID 40656893, 2025).
tumor (continued). "While IL-4R signaling promotes tumor progression and immune evasion, IL-24 acts as a natural brake on tumor growth." (PMID 40508013, 2025). "In particular, signaling through the interleukin-4 receptor alpha (IL-4Rα) has emerged as a critical modulator of tumor cell behavior." (PMID 40508013, 2025). "The interaction between tumor cells and other cell types via the interleukin‐4 (IL4)/IL4 receptor (IL4R) pair was considerably enriched in cGAS+/STING+ Tfh tumor cells." (PMID 38145335, 2024). "Cellular internalization, macrophage reprogramming and signal pathways, and tumor growth and metastasis by IL4R-Abx were examined." (PMID 38646639, 2024). "The miRNA-34a/Tat-A86 nanoformulation exhibited high suitability for miRNA-34a delivery to tumor sites by actively targeting IL-4R, a receptor highly expressed in most types of solid tumors." (PMID 38802812, 2024). "A similar pattern of tumor homing by IL4R-Abx was noted in mice bearing subcutaneous LLC lung tumor." (PMID 38646639, 2024). "IL4R-Abx accumulated at tumors, heightened immune-stimulatory cells while reducing immune-suppressing cells, and hampered tumor growth and metastasis in mice more efficiently than Abx and Ctrl-Abx." (PMID 38646639, 2024). "IL4R-Abx decreased the population of Ki67+ proliferating cells and IL4R-expressing cells in tumor tissues more efficiently than Abx when systemically administered at 10 weeks of age (5 mg/kg body weight, weekly for 4 weeks)." (PMID 38646639, 2024). "Because the liver was larger than tumor, the relative amount of paclitaxel in the liver after IL4R-Abx treatment was lower compared to tumor, while the ex vivo fluorescence signals of the liver were apparently high." (PMID 38646639, 2024). "Bone-marrow-associated macrophages (BMMs) derived from the classical monocytes promote breast cancer metastasis to bones in an IL4R+ dependent manner which is anticipated to be crucial for the polarization and pro-tumor function of BMMs." (PMID 39497943, 2024). "At the same time, IL4R‐Exo (si/mi) inhibits tumour growth by carrying miR‐511‐3p to reprogram TAM into M1‐like macrophages." (PMID 38572668, 2024). "IL4 and IL4R expression was higher in Tfh tumor cells in the RR group, whereas IL‐4+/CD4+ cells and IL‐4R+/CD20+ cells showed cell communication." (PMID 38145335, 2024). "Mice bearing 4T1 tumor were injected intravenously (weekly for 4 weeks) with IL4R-targeted and untargeted Abx." (PMID 38646639, 2024). "Whole-body fluorescence imaging acquired at 6 h after IL4R-Abx injection revealed higher levels of fluorescence signals at the tumor site and lower levels of background signals compared to Ctrl-Abx." (PMID 38646639, 2024). "A recent study established a bone metastasis model of colorectal cancer (CRC) using MC-38 or CT-26 cells in mice and demonstrated that IL4Rα expression is significantly upregulated in osteoclast precursors (OCPs) stimulated by tumor-conditioned medium (CM)." (PMID 39125732, 2024). "These cytokines primarily signal through the type II IL-4R, composed of IL-4Rα and IL-13Rα1, which is expressed in a wide array of epithelial tumor cells." (PMID 38519926, 2024). "Similar to tumor tissues, IL4R-Abx changed immune cell population in the spleen of tumor-bearing mice and improved antitumor immunity more efficiently than Abx and Ctrl-Abx." (PMID 38646639, 2024). "Histological analysis further revealed higher levels of accumulation by IL4R-Abx than Ctrl-Abx in 4T1 tumor tissues where IL4R was abundantly expressed." (PMID 38646639, 2024). "In tumor tissues, significantly higher amounts of paclitaxel were detected with minimal accumulation at control organs in mice injected with IL4R-Abx compared to Abx and Ctrl-Abx." (PMID 38646639, 2024). "In LLC lung tumor mice, IL4R-Abx decreased the tumor volumes, tumor weights, and number of metastatic tumor nodules in the lungs more efficiently than Abx and Ctrl-Abx." (PMID 38646639, 2024).